RNU6-378P (RNA, U6 small nuclear 378, pseudogene)
Gene: Small nuclear RNA gene on chromosome 5 (32,309,662 to 32,309,768, forward strand). Ensembl gene ENSG00000207052.
Homologues: Orthologues: chimpanzee U6 (99% identical), macaque U6 (94% identical), mouse Gm24448 (91% identical), guinea pig U6 (90% identical), guinea pig U6 (84% identical). Paralogues in human: RNU6-25P (95% identical), RNU6-33P (95% identical), RNU6-1 (94% identical), RNU6-2 (94% identical), RNU6-3P (94% identical), RNU6-48P (94% identical), RNU6-4P (94% identical), RNU6-5P (94% identical), RNU6-6P (94% identical), RNU6-9 (94% identical), RNU6-116P (93% identical), RNU6-12P (93% identical), and 1288 more.